BRAF (B-Raf proto-oncogene, serine/threonine kinase)
Diseases named in the same sentence as BRAF in open-access papers (continued):
Sharing a sentence is not in itself a finding about the gene and the disease.
tumor (continued). "In MSI tumours, the most frequently mutated known cancer genes were ACVR2A (9/9, 100%), MSH3 (5/9, 56%), FBXW7 (5/9, 56%), and BRAF (5/9, 56%)." (PMID 30894686, 2019). "Genomic DNA was isolated from whole blood for the analysis of VEGF-A (rs2010963, 1570360, rs699947), ICAM-1 (rs5498, rs1799969) SNPs and from tumor tissue for the detection of genomic variants in KRAS, NRAS, BRAF genes." (PMID 31752122, 2019). "Most importantly, a similar trend was observed in tumour samples from patients undergoing treatment with BRAF and MEK inhibitors." (PMID 30277012, 2019). "We propose that B2M testing is a useful adjunct to routine MMR testing and should be incorporated into a bowel tumour‐specific assay in conjunction with MLH1, KRAS, NRAS and BRAF status to provide an overall recurrence risk for individual patients." (PMID 31062389, 2019). "We chose a novel ERK1/2-selective pharmacologic inhibitor, SCH772984, which has shown cellular potency in tumor cells with BRAF, NRAS, or KRAS mutations and induces tumor regressions in xenograft models at toxicity-free doses." (PMID 31133044, 2019). "In this review we outline the current knowledge of BRAF gene alterations for the common tumor entities in children and adults." (PMID 31181803, 2019). "It is the unintended consequences of these evolutionary established feedback loops that limit overall tumour responses to BRAF inhibitors." (PMID 31416288, 2019). "To definitively establish the extent of tumor response, we excised the tumor site from several BRAF/MCL-1 inhibitor-treated mice." (PMID 31727958, 2019). "In our study, K1 cells exert BRAF mutation, the tumor-promoting role of HSDL2 gene, or its interaction network in PTC presenting BRAF-wt remained poorly known." (PMID 31101684, 2019). "Out of 30 cases, 28 cases showed positive BRAF V600E signal in 100% of tumor cells and 2 cases showed positive staining in 90% and 85% of tumor cells, respectively." (PMID 29127628, 2019). "TEADs play important roles in tumor progression and drug resistance downstream of the hyperactivating mutations on EGFR, KRAS, or BRAF." (PMID 31212916, 2019). "One tumor (patient #1) showed patchy positive staining for BRAF V600E, consistent with the BRAF c.1799 T > A p.(V600E) mutation detected on NGS." (PMID 31046843, 2019). "Tumour samples from all patients were screened for known hotspot mutations in KRAS, BRAF and NRAS as part of routine diagnostic examination." (PMID 31395942, 2019). "Thirty-one tumors presented concomitant mutations in two genes; three tumors presented concomitant mutations in three genes including one tumor with BRAF, NRAS and PIK3CA concomitant mutations and two tumors with BRAF, KRAS, and PIK3CA concomitant mutations." (PMID 31036005, 2019). "Particularly illustrative in this regard is case #10 with a primary tumor that was BRAF-positive and KRAS-negative." (PMID 30611220, 2019). "It is worth noting that the number of tumours exhibiting BRAF K601E, TERT, RET/PTC1, and PAX8-PPARγ were too low to establish statistical significance." (PMID 31623671, 2019). "Although both genetic and epigenetic factors contribute to drug resistance, the intricacies of the interplay between the two groups of mechanisms and their control of plasticity and tumor heterogeneity in BRAF-mutant cancers remains to be fully elucidated." (PMID 31581557, 2019). "In an attempt to overcome this shortcoming, the current study was corrected for right-sidedness of the primary tumour, which is associated with KRAS and BRAF mutational status." (PMID 30637550, 2019).
tumor (continued). "All except two of these shared variants (BRAF hotspot V600E in sync_4 and XPNPEP1 R204H in sync_11 (tumours sync_11–2 and sync_11–3)) were frameshift mutations." (PMID 30894686, 2019). "In FFPE CRC tissue, the amount of Fn DNA was associated with proximal tumor location (p = 0.009), MSI-positive (p < 0.0001), BRAF mutated tumors (p = 0.002), and the loss of expression of mismatch-repair proteins MLH1 (p < 0.0001) and PMS2 (p < 0.0001)." (PMID 31555583, 2019). "BRAF mutational analysis was performed on all MSI-H cases with only 10% (3/31) harbouring a mutation, and all 3 (3/13; 23%) occurred in dMLH1 tumours." (PMID 31636305, 2019). "The oncogenic mutations in BRAF gene result in constitutive activation of the MAPK signaling pathway, leading to increased cell proliferation, resistance to apoptosis and tumor progression." (PMID 29127628, 2019). "In brain tumors, cases with concurrent mutations of BRAF and the TERT promoter have been identified and appear to be associated with an aggressive tumor biology." (PMID 31391125, 2019). "A number of other small molecule inhibitors targeting BRAF have also been evaluated in vitro and are currently in clinical development for their anti-tumor activity against V600E mutant cancers." (PMID 30975211, 2019). "In one study the cases were scored as positive for BRAF V600E staining when only ≥20% tumor cells showed positive signal in one study." (PMID 29127628, 2019). "Based on our findings and consistent with other literature reports, the majority of BRAF V600E positive cases demonstrate a uniform or nearly uniform, diffuse staining pattern present in the majority of tumor cells." (PMID 29127628, 2019). "The patient-derived tumor specimens in this study represented a considerable amount of heterogeneity including different site of diagnosis, and the status of BRAF activation." (PMID 31118427, 2019). "Furthermore, compared to mutational status analysis (RAS or BRAF) included in recently proposed clinical risk scores, integrating sidedness gives an appealingly simple possibility to indirectly include information on tumour biology into preoperative stratification." (PMID 31150437, 2019). "A previous study revealed that genetic alternations such as TERT mutations, BRAF V600E mutations, and RET/PTC rearrangement all contributed to the tumor proliferation and metastasis." (PMID 31583243, 2019). "The KIAA1549-BRAF fusion gene, resulting from duplication of the BRAF gene at 7q34, is used as a marker of tumor derived cells and phenotypically distinct tumor cells expressing vascular markers; it is the most frequent genetic alteration in PA (>70%)." (PMID 31329636, 2019). "Mutant BRAF is a bona fide “driver oncogene”, since mutant BRAF inactivation often induces cancer cell toxicity, which indicates the establishment of an acquired dependency of tumor cells on oncogenic, mutant forms of BRAF." (PMID 31426419, 2019). "The pediatric BRAF V600E CNS-JXG neoplasms in this series share histologic and variable clinical/radiographic overlap with adult ECD cases, including one classic pediatric ECD." (PMID 31685033, 2019). "Here we show that the novel miR-550a-3-5p acts as a tumor suppressor and reverses BRAF inhibitor resistance through the direct targeting of YAP." (PMID 29844307, 2018). "This lower survival rate for subtype 2 tumours suggests that the combination of CIMP and BRAF mutation confers a poor prognosis in stable tumours, whereas the same combination in tumours with MSI (i.e., subtype 1) evolves in a completely different way." (PMID 30188916, 2018).
tumor (continued). "Our results demonstrated that AZ304, a dual BRAF kinase inhibitor, exerts potent anti-tumour effects on both wild type and mutant BRAF cancer lines." (PMID 29755114, 2018). "In xenograft studies, IT-139 decreased BRAF inhibitor upregulation of GRP78 expression in the tumor, while having minimal effect on GRP78 expression in the adjacent normal cells." (PMID 30038714, 2018). "Further, activated MYC and RAS or the downstream RAS effector BRAF synergistically induce tumor development in vivo in various transgenic mouse tumor models." (PMID 30526305, 2018). "Genotyping of RAS/BRAF in tumor tissue and ctDNA was determined by ARMS PCR and with a 40-gene panel using NGS, respectively." (PMID 29707525, 2018). "The aim was to study the dynamics in circulating BRAF DNA in response to BRAFi combination therapies (MEKi and EGFRi) and correlate these information's to tumor characteristics and clinical outcomes." (PMID 30220966, 2018). "Despite these observations, BRAF V600E protein expression independently predicted reduced survival, separately, and distinctly from mitotic rate, presence of ulceration, and tumor thickness." (PMID 29148538, 2018). "Studying the combination of changes in signaling and metabolic networks that occur in cells as a result of the KRAS and BRAF oncogenes should provide insights into both fundamental tumor processes and the mechanisms by which they circumvent therapies." (PMID 29907857, 2018). "In tumor cells, acetoacetate enhances BRAF-V600E binding to MEK1 and thereby activates the MEK–ERK signaling axis and contributes to BRAFV600E tumor growth." (PMID 29725585, 2018). "TCPTC was associated with a patient age >45 years, tumor multifocality, extrathyroidal extension, a higher T stage, advanced AJCC TNM stages, BRAF V600E mutation, and poor disease-free survival." (PMID 30572540, 2018). "We plan to compare cSCC samples resulting from various etiologies, including BRAF inhibitor- induced cSCC and ultraviolet light-induced cSCC, to determine if there are unique characteristics in the cSCC from our ICPI- associated tumor cohort of patients." (PMID 30400822, 2018). "At the molecular level, GGs are characterized by the frequent mutations of the BRAF gene (BRAFV600E), ranging from 10 to 60% according to tumor location, with the highest frequency in cerebral tumors." (PMID 30279357, 2018). "PLX4032, also known as vemurafenib, is an inhibitor that binds to the ATP-binding site of mutated BRAF kinase, inhibiting ERK signaling only in tumor cells expressing BRAFV600E mutations." (PMID 30104528, 2018). "We present the case of a patient with a multiply recurrent pleomorphic xanthoastrocytoma which demonstrated a sustained partial response to a combination regimen of the BRAF inhibitor vemurafenib and tumor treating fields." (PMID 29708404, 2018). "For patients with BRAF-mutant tumors and a high tumor load, targeted therapy is frequently preferred, as therapy responsiveness occurs more quickly." (PMID 30237393, 2018). "In conclusion, our results suggested that the novel miR-550a-3-5p acts as a tumor suppressor and reverses BRAF inhibitor resistance through the direct regulation of YAP in multiple cancer cells." (PMID 29844307, 2018). "Among all BRAF mutant tumours, the most common genotype was V600E (70.0%), followed by V600K (22.9%) and less common genotypes (7.1%)." (PMID 29755118, 2018). "Presence of KRAS, PIK3CA, and BRAF mutations was tested in cfDNA and tumor tissue with an overall concordance rate of 76% for KRAS, 88% for PIK3CA, and 97% for BRAF mutations." (PMID 29441349, 2018).
tumor (continued). "In summary, low LRP1 expression evaluated by immunohistochemistry and by qRT-PCR in two independent cohorts is strongly associated with right tumor location, MSI-H, BRAF mutation and CIMP-H." (PMID 29507659, 2018). "This classification takes into account different molecular signatures of the primary tumor, such as MSI, hypermutator status, BRAF and KRAS mutations, WNT and MYC activation, TGF-β activation, and methylation status." (PMID 30282914, 2018). "In contrast, only the TNM stage at diagnosis, the tumor size, microsatellite instability and the BRAF status showed a prognostic impact on OS (in the univariate analysis) among our cases." (PMID 29844874, 2018). "The results were extrapolated into an in vivo mouse model with implanted mutant KRAS and BRAF cancer cells in which tumor growth was slowed when the animals were administered high doses of vitamin C by daily intraperitoneal injection of 4 g/kg." (PMID 30018566, 2018). "The biomarker analysis set for predictive genomic markers (KRAS, NRAS, BRAF, or PIK3CA mutations) included 46 subjects with tumour tissue sequenced." (PMID 30425349, 2018). "For example, the RAS/BRAF/MEK signal transduction pathway is known to play an important role in tumour development in multiple cancer types." (PMID 29950679, 2018). "Preclinical studies suggest that BRAF inhibitors enhance anti-tumor immunity and antigen presentation." (PMID 30053905, 2018). "BRAF V600E mutation was found in 24 of the 60 (40%) PTC cases, with mean tumor size of 1.59 ± 1.20 cm." (PMID 30509240, 2018). "Differently, our data showed higher p16 (INK4α)-positive rates in BRAF V600E-mutated MA than in the BRAF wild-type, which increased the relationship between BRAF V600E and the p16 (INK4α) senescence marker in those indolent neoplasms." (PMID 30111351, 2018). "This is the basis for one of the main treatment strategies for this tumor type, the targeted therapy with BRAF and MEK inhibitors." (PMID 30237393, 2018). "According to previous studies, patients with RCC always presented with subtle or occult symptoms, higher tumour stage, poor differentiated, higher percentage of CIMP, MSI, and BRAF mutation positive." (PMID 30245712, 2018). "Quite identical mutation patterns between primary tumors and metastatic lesions were found for BRAF and NRAS genes; mutations of CDKN2A gene appeared to be instead selected during tumor progression." (PMID 29492214, 2018). "The most frequently mutated genes across all tumor types included KRAS (30 patients), PIK3CA (16 patients), BRAF (6 patients), EGFR (5 patients), NRAS (4 patients), and ERBB2 (3 patients)." (PMID 29854313, 2018). "The concordance between BRAF and KRAS mutation analysis in tumor tissue and matched plasma was analyzed further." (PMID 30373199, 2018). "The primary aim of this study was to explore if patients with BRAF or NRAS mutant tumours compared to patients with wild-type tumours have an increased risk of developing disease recurrence following a negative SLNB." (PMID 29755118, 2018). "Recent studies have provided evidence on the prognostic and likely predictive role of SMAD4 and BRAF, two genes that are currently considered tumor suppressors in CRC." (PMID 30282914, 2018). "Complete and partial responses to BRAF inhibition have been observed in patients with complete loss of PTEN tumour expression and with PIK3CA tumour-associated activating mutations." (PMID 30237495, 2018). "BRAF V600E specific cells showed a Th1 memory phenotype, were preferentially localized to the tumor site, and expanded and persisted in blood greater than 2 years after TIL therapy." (PMID 30400835, 2018). "The oncogenic activation of BRAF can eventually lead to tumor generation in mouse models, but with a slow kinetics of tumor development." (PMID 29652830, 2018).
tumor (continued). "All patients’ tumor tissues were tested for the presence of BRAF V600E, either by IHC or NGS-50 gene somatic mutation analysis panel, 6 (50%) of which harbored a BRAF V600E mutation." (PMID 29996921, 2018). "Primary tumor site, ECOG performance status, and BRAF status were significantly associated with PFS and OS." (PMID 29522543, 2018). "Thirty-one cfDNA samples positive for IDH1, KRAS, PIK3CA, NRAS, AKT, BRAF, and IDH2 mutations in tumor tissue were selected for ddPCR, MassARRAY and NGS comparison." (PMID 29535804, 2018). "The BRAF V600E mutation was found in 24 (40%) of the 60 PTC cases, with the mean tumor size being 1.59 ± 1.20 cm." (PMID 30509240, 2018). "Following a positive response towards BRAF-targeting drugs, tumor cells begin to exhibit resistance within 6–7 months." (PMID 30053879, 2018). "The results showed that TCPTC was significantly correlated with a patient age >45 years, tumor multifocality, extrathyroidal extension, a higher T stage, advanced AJCC TNM stages, and BRAF V600E mutation." (PMID 30572540, 2018). "Overall, BRAF, NRAS, and CDKN2A were found mutated in 62.5%, 12.5% and 59% cell lines and in 47%, 16%, 12% tumor tissues, respectively." (PMID 29492214, 2018). "Using neurospheres with BRAF activation, tumor proliferation in nude mice was observed, followed by a period of growth arrest, thus indicating that BRAF induces both cell growth and subsequent cellular arrest." (PMID 30279357, 2018). "In its absence, the effects of MEK inhibitors have been studied in tumors expressing mutated BRAF and KRAS; however, they led to tumor resistance through feedback and crosstalk mechanisms within the EGFR/MAPK and EGFR/PI3K signaling pathway." (PMID 29907857, 2018). "These members suggested using either anti-PD-1 therapy or D/T, while others preferred the use of D/T if the tumor was BRAF mutant or enrollment onto a clinical trial incorporating ipilimumab at 3 mg/kg." (PMID 29848375, 2018). "BRAF mutation was detected in the ctDNA of 1 out of 3 patients with BRAF mutant tumours and in 1 additional patient with a KRAS mutant/BRAF wild-type tumour." (PMID 29362371, 2018). "Patients with BRAF V600E had significantly higher levels of midnight plasma ACTH (P = 0.023, Mann–Whitney U-test) and midnight serum cortisol (P = 0.007, Mann–Whitney U-test), but similar tumor sizes, when compared with patients carrying wild-type BRAF/USP48." (PMID 30093687, 2018). "Metastatic CRC patients with BRAF mutant tumours are characterised by poor response rates to the anti-EGFR monoclonal antibodies (moAb) panitumumab and cetuximab and poor prognosis, with a median overall survival of only about 9 to 12 months." (PMID 29895949, 2018). "A tissue biopsy was collected when a patient with an initial RAS/BRAF WT tumour developed secondary resistance to anti-EGFR-based therapy." (PMID 29895949, 2018). "The most frequently mutated genes across all tumor types included KRAS, PIK3CA, BRAF, EGFR, NRAS and ERBB2." (PMID 29854313, 2018). "Six hundred eight two (51%) patients’ tumours were assessed for BRAF and NRAS mutation status; BRAF V600 and NRAS mutations were detected in 303 (44%) and 134 (20%) tumours tested." (PMID 30010756, 2018). "Now, the finding that driver somatic mutations in BRAF in 55% of cases with LCH and activation of the RAS-RAF-MEK-ERK pathway in nearly all of the cases satisfied evidence for LCH to be a neoplastic disease." (PMID 29587787, 2018). "In 15 out of 433 cases (3.5%) a BRAF-mutation was found and in 12 out of 433cases (2.8%) an H3F3A-mutated tumor (K27 M: 9 (2.1%), G34 M: 3 (0.7%))." (PMID 30470264, 2018). "In conclusion, our study demonstrates that ≥20% tumor cellularity is required to identify T790M mutation as the cause of TKI resistance, and to detect HER2/BRAF/PIK3CA mutations in biopsy samples using the amplification‐based NGS testing." (PMID 29518290, 2018).